MIR139 (microRNA 139)
Synonyms: hsa-mir-139; MIR139-3p; MIRN139; mir-139
Gene: MicroRNA gene on chromosome 11 (72,615,063 to 72,615,130, reverse strand). Ensembl gene ENSG00000272036.
Gene Ontology:
Cellular component: RISC complex
Homologues: Orthologues: chimpanzee ptr-mir-139 (100% identical), macaque MIR139 (100% identical), mouse Mir139 (100% identical), pig MIR139 (100% identical), rat Mir139 (100% identical), guinea pig MIR139 (99% identical), rabbit MIR139 (85% identical), dog MIR139 (82% identical), tropical clawed frog xtr-mir-139 (72% identical).
Diseases named in the same sentence as MIR139 in open-access papers:
MIR139 is named in the same sentence as 6 diseases in open-access papers, as found by Europe PMC text mining. Sharing a sentence is not in itself a finding about the gene and the disease. The quoted sentences say what the papers report.
acute myeloid leukemia (3 papers, 2022 to 2025). Acute myeloid leukemia (AML) is a group of neoplasms arising from precursor cells committed to the myeloid cell-line differentiation. "Although the polymerase subunit POLR2M showed favorable prognosis (OS) for CCC in our cohort, it has been found to be associated with poor prognosis in acute myeloid leukemia by silencing the MIR139 tumor suppressor." (PMID 40778374, 2025). "There is limited research on AC127521.1 and LINC02580, but studies have shown that AC127521.1 can promote the malignant biological behavior of acute myeloid leukemia by regulating the expression of SPNS3 mediated by MIR-139." (PMID 38684626, 2025). "MIR139 is a tumor suppressor and is commonly silenced in acute myeloid leukemia (AML)." (PMID 34741119, 2022).
leukemia (2 papers, 2022). A malignant (clonal) hematologic disorder, involving hematopoietic stem cells and characterized by the presence of primitive or atypical myeloid or lymphoid cells in the bone marrow and the blood. "Notably, the enhanced expansion capacity of MLL-AF9-Mir139KO cells compared with MLL-AF9 cells indicate that complete loss of Mir139 is a selective advantage for leukemia outgrowth in vitro." (PMID 34741119, 2022). "A panel of 22 Mir139 KO and 18 Mir139 WT mice were monitored for the development of leukemia and other types of cancer for 2 years." (PMID 35269391, 2022). "There is emerging evidence that MIR139 is a tumor suppressor in various types of solid cancer and leukemia." (PMID 34741119, 2022). "Whether MIR139 plays a major role in NOTCH1 signaling during leukemia development remains to be investigated." (PMID 35269391, 2022). "Furthermore, our findings reveal a PRC2-dependent POLR2M-mediated silencing mechanism of the MIR139 tumor suppressor in MLL-AF9 leukemia." (PMID 34741119, 2022).
colitis (1 paper, 2022). Inflammation of the colon. "For instance, other investigators have found that Mir139 KO mice are highly susceptible to the development of dextran sulfate salt (DSS)-induced colitis and colon cancer." (PMID 35269391, 2022). "They found that the expression of Mir139 dampens the expression of phosphorylated MAPK, NF-κB and STAT3, all factors that drive inflammation and colitis-associated oncogenesis." (PMID 35269391, 2022).
tumor (2 papers, 2022). "Reactivation of MIR139 expression in tumor cells causes inhibition of tumor cell expansion and induction of cell death by the repression of oncogenic mRNA targets." (PMID 35269391, 2022). "We provide evidence that Mir139 is a tumor suppressor that is targeted by PRC2 downstream of MLL-AF9." (PMID 34741119, 2022). "The proliferation rate of Mir139 KO tumor cells was enhanced, confirming the growth advantage of Mir139 KO tumor cells." (PMID 35269391, 2022). "MIR139 acts as a critical tumor suppressor by tuning the cellular response to different types of stress, including DNA damage, and by repressing oncogenic signaling pathways." (PMID 35269391, 2022). "Mir139 KO mice were also used for the investigation of MIR139 tumor suppressor functions in different types of cancer." (PMID 35269391, 2022). "Our study has elucidated the molecular silencing mechanism of MIR139 and provides insight into its tumor suppressor activity, offering potential targets of intervention for the poorly prognostic MLL-AF9 AML." (PMID 34741119, 2022). "Recently, novel insights into the mechanism of MIR139 silencing in tumor cells have been described." (PMID 35269391, 2022). "It becomes increasingly evident that MIR139 is a critical tumor suppressor gene in different types of cancer and that the deregulation of MIR139 transcription, processing or targeting activity inhibits its tumor-suppressive activities." (PMID 35269391, 2022). "Accordingly, MIR139 overexpression resulted in reduced overall protein expression, which may explain the inhibitory effects of miR-139 expression on tumor cell proliferation and survival." (PMID 35269391, 2022). "Furthermore, we have identified MIR139 targets that mediate its tumor suppressor activity in AML." (PMID 34741119, 2022).
cancer (1 paper, 2022). A tumor composed of atypical neoplastic, often pleomorphic cells that invade other tissues. "Some of these MIR139-silencing mechanisms have been demonstrated in different types of cancer, suggesting that these are more general oncogenic events." (PMID 35269391, 2022). "In this review, we discuss the different aspects of MIR139 as a tumor suppressor gene and give an overview on different transcriptional mechanisms regulating MIR139 in oncogenic stress and across different types of cancer." (PMID 35269391, 2022). "Multiple well-known oncogenes silence the expression of MIR139 in cancer." (PMID 35269391, 2022). "Although the mechanism of MIR139 silencing in various types of cancer is not fully unraveled, targeting MIR139 to reactivate its expression is a promising avenue for novel targeted therapies." (PMID 35269391, 2022).
MIR139 also shares sentences with these, for which no sentence is quoted: colorectal cancer (1 paper).